MYADML2 (myeloid associated differentiation marker like 2)
Synonyms: LOC255275
Tractability: Antibody: UniProt predicts a signal peptide or a membrane-spanning region.
Gene: Protein-coding gene on chromosome 17 (81,939,645 to 81,947,233, reverse strand). Ensembl gene ENSG00000185105.
Subcellular location: Membrane
Gene Ontology:
Molecular function: protein binding
Cellular component: cytoplasm; membrane
Genetic constraint (gnomAD): Loss-of-function variants: 17 observed, 15.5 expected, observed/expected ratio (o/e) 1.1, 90% interval 0.75 to 1.63. The upper end of that interval is the gene's LOEUF score, 1.63, which puts it in group 6 of 6, group 1 being the genes least tolerant of losing a copy. Missense variants: 422 observed, 424.79 expected, observed/expected ratio (o/e) 0.99, 90% interval 0.92 to 1.08. Synonymous variants: 210 observed, 204.03 expected, observed/expected ratio (o/e) 1.03, 90% interval 0.92 to 1.15.
Homologues: Orthologues: chimpanzee MYADML2 (99% identical), macaque MYADML2 (97% identical), pig MYADML2 (93% identical), rat Myadml2 (93% identical), dog MYADML2 (92% identical), mouse Myadml2 (92% identical), rabbit MYADML2 (92% identical), guinea pig MYADML2 (90% identical), tropical clawed frog myadml2 (61% identical), zebrafish myadml2 (61% identical). Paralogues in human: MYADM (39% identical).
Diseases named in the same sentence as MYADML2 in open-access papers:
MYADML2 is named in the same sentence as 4 diseases in open-access papers, as found by Europe PMC text mining. Sharing a sentence is not in itself a finding about the gene and the disease. The quoted sentences say what the papers report.
hepatocellular carcinoma (1 paper, 2024). A malignant tumor that arises from hepatocytes. "Genome-wide screen by CRISPRa library in vivo for drivers of hepatocellular carcinoma (HCC) progression revealed that overexpression of XAGE1B, PLK4, LMO1 and MYADML2 genes promoted HCC cell proliferation and invasion, which were suppressed by their inhibition." (PMID 39696697, 2024).
mastitis (1 paper, 2021). Inflammation of breast tissue during lactation or postpartum due to an obstructed duct or infection. "Myadml2, which encodes myeloid-associated differentiation marker-like 2, may influence the ability of dairy cows to resist the inflammation response of mastitis." (PMID 35036173, 2021).
tumor (1 paper, 2023). "This is especially evident in the cases of MALL, PLLP, and MYADM, whose function in normal and tumor cells needs further investigation using established cell model systems, and that in the case of MYADML2, which is yet to be examined." (PMID 37345137, 2023).
MYADML2 also shares sentences with these, for which no sentence is quoted: asthma (1 paper).